STAT3 (signal transducer and activator of transcription 3)
Diseases named in the same sentence as STAT3 in open-access papers (continued):
Sharing a sentence is not in itself a finding about the gene and the disease.
glioma (continued). "Similarly, in gliomas, a gain-of-function mutation in STAT3 results in increased immunosuppression and heightened tumour invasion, whilst within the setting of DMGs specifically it is known that STAT3 is elevated." (PMID 34944870, 2021). "In view of this, we hypothesized that STAT3 overexpression is associated with glioma." (PMID 30134017, 2018). "High levels of STAT3 protein expression have been associated with poor tumor differentiation and/or development of metastasis and poor survival rates in leukemia, lymphoma, osteosarcoma, glioma, gastric adenocarcinoma, colorectal cancer, bladder cancer, and cervical squamous cell carcinoma cases." (PMID 24662938, 2014). "In previous research of our group, saw palmetto extract was shown to markedly inhibit the proliferation of human glioma cells, and the underlying mechanism may be associated with the inhibition of signal transducer and activator of transcription 3 phosphorylation." (PMID 25009620, 2014). "IHC analysis demonstrated increased STAT3-positive cells in higher-grade glioma tissues, with the highest levels observed in recurrent GB tissues." (PMID 41560805, 2026). "In glioma, KAT6B facilitates the acetylation of histone H3 at lysine 23 and the enrichment of RNA polymerase II at the STAT3 promoter in glioma cells, thereby promoting STAT3 expression and exerting an inhibitory effect on ferroptosis." (PMID 41513612, 2026). "We first analyzed the TCGA and CGGA databases, which revealed elevated STAT3 expression in GB, with expression levels correlating positively with glioma grade." (PMID 41560805, 2026). "In this study, we demonstrate that TRPC1 promotes glioma cell migration by increasing Signal transduction and transcription activator 3 (STAT3) protein levels." (PMID 41787243, 2026). "SIRT7 is markedly overexpressed in higher-grade gliomas and contributes to cell proliferation, invasion, and chemoresistance through regulation of the ERK/STAT3 and IDH1-associated metabolic pathways." (PMID 40710366, 2025). "There is strong evidence that STAT3, a key player in many immune inhibitory pathways, shows higher activation in glioma cells but also in TAMs, driving immune suppression." (PMID 41157253, 2025). "Research demonstrates that PDGFRα signaling is crucial for glioma-like hyperplasia and the preservation of glioma stem cell characteristics via pathways such as PDGFRα/STAT3/RB1." (PMID 40332008, 2025). "We have demonstrated that F3-T3 facilitates the malignant progression of glioma cells via the activation of the STAT3 signaling." (PMID 40265014, 2025). "Signalling crosstalk between NF-κB and STAT3, which is a feature shared in cancer, including glioma, was apparent in cell line models of TSC." (PMID 41013689, 2025). "The colony formation assay showed a distinct decrease in both proliferation and colony-forming ability of glioma cells post-STAT3 knockdown." (PMID 40265014, 2025). "At present, the literature on the inhibitory effect of metformin on glioma stem cells mainly focuses on the studies on the AMPK-mTOR/STAT3, AMPK-FOXO3 and AMPK-P13K/AKT pathways of MET." (PMID 39944825, 2025). "The role of the STAT3 pathway in gliomas was also reinforced through bioinformatic analysis and immunohistochemistry (IHC) on tissue microarrays (TMA)." (PMID 40265014, 2025). "Several eRNAs, including TMZR1-eRNA and LINC02454, influence sensitivity to temozolomide (the main chemotherapeutic agent for glioma) by modulating STAT3 and DDR1 signaling." (PMID 41154382, 2025). "Beyond STAT3, liposomal RNA interference strategies have also been applied to target other tumor-intrinsic drivers in glioma." (PMID 40725021, 2025). "Quercetin significantly reduces T98G and U87 glioma cell proliferation and migration by inhibiting STAT3 phosphorylation, primarily through the downregulation of two STAT3 target genes: cyclin D1 and MMP-2." (PMID 40733274, 2025).
glioma (continued). "Calanquinone A inhibits glioma cell proliferation and migration by targeting the STAT3/c-Myc and STAT3/MMP9 signaling pathways." (PMID 40759869, 2025). "ITGA2 is enriched in glioma stem-like cells to promote invasion by modulating PD-L1 and activating STAT3 phosphorylation, enhancing epithelial-mesenchymal transition." (PMID 40885689, 2025). "To investigate the expression of p-STAT3 protein in glioma tissues within a clinical setting, we utilized IHC on TMAs sourced from our department." (PMID 40265014, 2025). "Conversely, overexpression of KAT6B suppresses erastin-induced lipid ROS and ferroptosis in these cells and deletion of STAT3 reverses KAT6B-mediated glioma cell ferroptosis." (PMID 41457120, 2025). "Signal transducer and activator of transcription 3 (STAT3) promotes angiogenesis, and elevated STAT3 expression levels in gliomas correlate with unfavorable prognostic outcomes." (PMID 40075568, 2025). "By inhibiting the JAK/STAT3 signaling pathway, convallatoxin inhibited proliferation, migration, invasion, and angiogenesis of glioma cells, proving to be a promising therapeutic candidate for gliomas." (PMID 40321161, 2025). "Among the model genes, CRNDE, a long non-coding RNA, is upregulated in various solid tumors and promotes malignant progression of glioma by regulating the miR-384/PIWIL4/STAT3 axis." (PMID 40130175, 2025). "STAT3 is turned on by signals including IL-6, IL-10, epidermal growth factor and fibroblast growth factor, making it a key player in glioma immune evasion." (PMID 41157253, 2025). "This study demonstrates that Calanquinone A effectively inhibits glioma cell proliferation and migration by targeting the STAT3/c-Myc and MMP9 signaling pathways." (PMID 40759869, 2025). "In hence, our findings clearly indicate that STAT3 signaling plays a significant role to the progression of glioma." (PMID 40265014, 2025). "The combination treatment of resveratrol and temozolomide demonstrates synergistic effects by inhibiting MGMT expression and downregulating the STAT3/Bcl-2/survivin signaling pathway, which leads to increased apoptosis and cell cycle arrest in glioma cells." (PMID 41009025, 2025). "Functional assays showed that NIBAN2 enhanced glioma cell aggressiveness by activating JAK2/STAT3 signaling and promoted tumor growth by preventing apoptosis and accelerating the cell cycle." (PMID 40944417, 2025). "In the CCK-8 assay, the proliferation induced by F3-T3 in glioma cells was diminished following STAT3 knockdown." (PMID 40265014, 2025). "The activated STAT3 in the ITE+PD1 group suggests that STAT3 inhibitors shall be explored as an addition to the current combination reported here, specifically in those gliomas with a STAT3 gene signature." (PMID 40283908, 2025). "Integrating KEGG enrichment analysis from RNA sequencing of F3-T3 glioma cells with GSEA results from the E-MTAB-6037 gene chip database, we suggest that F3-T3 enhances the EMT process in glioma through the activation of STAT3 signaling." (PMID 40265014, 2025). "The levels of survivin and Bcl-2, which are active in cell proliferation and maintenance of gliomas and are target genes of the STAT3 pathway, were decreased in Res/TMZ-treated cells." (PMID 41009025, 2025). "Its overexpression has been reported to suppress radio-sensitivity by activating STAT3 signaling in gliomas." (PMID 40718795, 2025). "Phosphorylated STAT3 (p-STAT3) in human gliomas influences inflammatory responses, with its expression varying significantly across glioma types and stages of pathology." (PMID 40075568, 2025). "It is noteworthy that, in contrast to the positive regulatory role of USP38 in malignancies such as gastric and colorectal cancers, USP38’s suppression of JAK2/STAT3 signaling pathway activation in glioma demonstrates its dual role in tumor regulation." (PMID 40936898, 2025).
glioma (continued). "Nevertheless, some studies suggest that CDK7 maintains glioma stemness and confers apoptosis resistance in A172 cells by activating pro-survival pathways such as STAT3 and Notch." (PMID 40843352, 2025). "To explore the role of the STAT3 signaling pathway in glioma, we analyzed both the expression levels of the STAT3 gene and its corresponding protein." (PMID 40265014, 2025). "Other BPAs, like CHE, inhibit non-small cell lung cells by downregulating β-Catenin, while NTD suppresses epithelial mesenchymal transformation and glioma stem cells by targeting the JAK2/STAT3 signaling pathway." (PMID 40630130, 2025). "STAT3 is a key transcription factor that is abnormally activated in a variety of tumors, including gliomas, and promotes tumor growth, invasion, and metastasis." (PMID 39944825, 2025). "And in the field of immunotherapy, a previous study found that miR-124 inhibits STAT3 signaling to enhance T cell-mediated immune clearance in glioma." (PMID 39865088, 2025). "In order to assess the potential therapeutic uses of NLP-EXOSOME COMPLEX-formulated siRNA both in vitro and in vivo, we specifically targeted STAT3, as it is known to be highly active in glioma and difficult to treat with traditional drugs." (PMID 40427146, 2025). "The interaction between NF-κB and STAT3 facilitates tumor progression and promotes the expression of stem-like traits in diverse malignancies, such as gliomas." (PMID 40869207, 2025). "TNF‐α/NF‐κB signaling is another key inflammatory axis: TNF‐α can stimulate glial and immune cells to produce IL‐6 and activate NF‐κB, which in turn sustains STAT3 signaling, thereby enhancing glioma cell proliferation and aggressiveness." (PMID 41354084, 2025). "Collectively, these findings indicate that F3-T3 activates STAT3 signaling, thereby enhancing the malignant progression of glioma cells." (PMID 40265014, 2025). "Stress-induced chromatin remodeling (e.g., via EZH2, H3K27ac modifications) and downstream transcriptional shifts (e.g., STAT3 activation) promote return to a resilient glioma stem cell phenotype." (PMID 41614813, 2025). "Collectively, these results indicated that NIBAN2 triggered glioma progression by stimulating the JAK2/STAT3/c‐Myc signaling pathway." (PMID 40944417, 2025). "For example, genetic silencing of a well-known histone acetyltransferase KAT6B reduces the enrichment of histone H3 lysine 23 acetylation on the STAT3 promoter region in glioma cell lines including U251 and LN229140." (PMID 41457120, 2025). "BACE1 also modulates the polarization of GAMs through activation of the JAK/STAT3 signaling pathway, a critical driver of immunosuppressive mechanisms in glioma." (PMID 41479886, 2025). "Astrocyte-derived CCL2 can bind CCR2 on glioma cells to maintain stemness characteristics by activating JAK2/STAT3-Notch signaling pathway." (PMID 40243478, 2025). "Activation of inflammatory pathways such as NF-κB and STAT3 not only promotes glioma cell invasion and angiogenesis but also sustains the stem-like properties of glioma stem-like cells (GSCs), ultimately contributing to tumor recurrence and poor prognosis." (PMID 40881678, 2025). "Preclinical evidence suggests that fluoxetine can radiosensitize glioma cells, inhibit STAT3-mediated metastasis in osteosarcoma, and reverse chemotherapy resistance." (PMID 41409248, 2025). "Given that IL‐6 contributes to glioma immune escape, combinations that pair PD‐1/PD‐L1 inhibitors with IL‐6/STAT3 pathway modulators (or related JAK/STAT interventions) merit prospective testing to couple immune reinvigoration with inflammation dampening." (PMID 41354084, 2025). "Mechanistically, HIF‐1α targeted NIBAN2 to upregulate it, thereby promoting glioma progression by stimulating the JAK2/STAT3/c‐Myc signaling axis." (PMID 40944417, 2025). "Overall, our findings demonstrate that F3-T3 enhances the proliferation, invasion, and migration of glioma cells primarily through activating the STAT3 signaling pathway." (PMID 40265014, 2025).
glioma (continued). "F3-T3 facilitates the proliferation, invasion, migration and EMT of glioma cells, thereby promoting their malignant progression through STAT3 signaling activation." (PMID 40265014, 2025). "To investigate the impact of STAT3 signaling on glioma, we conducted a series of comprehensive analyses." (PMID 40265014, 2025). "This is in line with studies demonstrating celecoxib-mediated inhibition of STAT3 phosphorylation in nasopharyngeal carcinoma cell lines and ibuprofen- and diclofenac-mediated decrease in the level of phosphorylated STAT3 in glioma cell lines." (PMID 40408503, 2025). "Correction analysis of STAT3 and FGFR3 with major glioma mutation types and pan-cancer analysis was conducted using The Cancer Genome Atlas (TCGA) database." (PMID 40265014, 2025). "Collectively, these results demonstrate that Calanquinone A suppresses glioma proliferation and migration by targeting the STAT3/c-Myc and MMP9 pathways." (PMID 40759869, 2025). "By targeting the STAT3 pathway, resveratrol not only suppresses glioma cell growth but also induces apoptosis and cell cycle arrest, potentially improving treatment outcomes in resistant GBM cases." (PMID 39769099, 2024). "Our previous research conducted on the STAT3 signaling pathway has provided evidence that inhibiting STAT3 signaling can induce apoptosis in glioma cells." (PMID 39153914, 2024). "Collectively, the data strongly indicate significant pathological implications of miR-410 and STAT3 in glioma." (PMID 38238515, 2024). "In line with this notion, inhibition of STAT3 in a murine model of glioma enhanced TNFα expression in microglia/macrophages, blocked tumor growth and improved survival." (PMID 38499808, 2024). "Overexpression of SRPK1 activates the Wnt/β-catenin (wingless-int1/β-catenin) and JAK-2/STAT-3 (Janus kinase 2/signal transducer and activator of transcription 3) signaling pathways, promoting the proliferation, migration, and invasion of gliomas." (PMID 38397980, 2024). "Inhibiting STAT3 signaling can impede glioma cell proliferation, induce apoptosis, and enhance the sensitivity of tumor cells to conventional therapies." (PMID 39153914, 2024). "The western blot and RT-PCR confirmed that the expression of STAT3 was significantly reduced in glioma cells stably transfected with Lv-NC, Lv-miR-410, and Lv-anti-miR-410, respectively." (PMID 38238515, 2024). "Compared to normal brain tissues, glioma tissue and cell lines had an elevated level of phosphorylated STAT3, which exacerbated glioma and contributed to drug resistance in malignant glioma cells." (PMID 39153914, 2024). "In contrast, the STAT3 expression was elevated in the Lv-anti-miR-410 glioma cell group contrasted to those in Lv-NC glioma cells as control." (PMID 38238515, 2024). "Overexpression of SRPK1 activates the Wnt/β-catenin and JAK-2/STAT-3 signaling pathways, promoting the proliferation, migration, and invasion of gliomas." (PMID 38397980, 2024). "Studies had shown that inhibiting of the IL-6/JAK2/STAT3 signaling pathway inhibited the proliferation of glioma cells and promotes apoptosis." (PMID 37642814, 2024). "We found that overexpression of CSMD1 in glioma cells resulted in a decrease in phosphorylation of both P65 and STAT3 as well as a decrease in secretion of both IL-6 and IL-8 when compared to the corresponding Ctrl glioma cells." (PMID 38561856, 2024). "Several studies showed that p-STAT3 is over-expressed in the majority of GBM patients and associated with mesenchymal differentiation and worse prognosis in gliomas, making the STAT3 signaling pathway an important therapeutic target for glioma treatment." (PMID 39153914, 2024). "SRPK1 regulates the proliferation, invasion, and migration of glioma cells through the Wnt/β-catenin/JAK-2/STAT-3 pathway." (PMID 38397980, 2024).
glioma (continued). "Another feedforward mechanism involves glioma-derived MCP-1/CCL2, which triggers the release of IL-6 from microglia, a ligand for signal and activator of transcription 3 (STAT3) pathway in gliomas." (PMID 38254796, 2024). "In glioma cell lines, the expression of all evaluated markers was downregulated in U87MG STAT3 KO variant compared to parent U87MG cells." (PMID 38654280, 2024). "The findings indicate that the reduction of STAT3 expression exhibited a partial phenocopy to the impacts of miR-410 upregulation in glioma cells." (PMID 38238515, 2024). "Our results indicated that epigenetically promoted silencing of miR-410 participates in oncogene STAT3 induction in glioma." (PMID 38238515, 2024). "In our study, we explore the EZH2–STAT3 signaling axis in pyroptosis of glioma cells through in vitro experiments, validating the relationship between EZH2, STAT3, and pyroptosis in glioma cells." (PMID 39069522, 2024). "Only HIF1A and STAT3 robustly showed significant positive correlations with METTL8 in all three glioma cohorts." (PMID 38744809, 2024). "The constitutive activation of STAT3 and the NF-kappa B signaling pathway led to the up-regulation of Notch pathway promoter expression in human glioma CSC, which determined a new therapeutic target for glioma therapy." (PMID 38790208, 2024). "Resveratrol holds promise as a supplemental therapy for gliomas, especially due to its interaction with the STAT3 (Signal Transducer and Activator of Transcription 3) signaling pathway." (PMID 39769099, 2024). "In order to conduct a more comprehensive examination of the connection between miR-410 and STAT3 in glioma cells, a luciferase activity assay was carried out." (PMID 38238515, 2024). "They demonstrated that the beta-catenin pathway regulates miR-21 expression in human umbilical vein endothelial cells and glioma cells and that this regulation is signal transducer and activator of transcription 3 (STAT3)-dependent." (PMID 38612895, 2024). "Along with the ICC findings, the immunofluorescence results showed that in the control group, p-STAT3 was primarily localized around the nuclear membrane and within the nucleus of glioma cells." (PMID 39153914, 2024). "In vivo and vitro investigations, both related to gain- and loss-of-function, reveal that restoration of miR-410 expression suppresses glioma cell growth and prompts cell apoptosis, particularly through directly targeting STAT3." (PMID 38238515, 2024). "The findings of the Luciferase reporter assay and western blot analysis indicate that miR-410 has a direct effect on the 3’-UTR of signal transducer and activator of transcription 3 (STAT3), thereby inhibiting its expression within glioma cells." (PMID 38238515, 2024). "They demonstrated that RECK is regulated by MRE from RECK-3′-UTR mediated by the beta-catenin/STAT3/miR-21 circuit in glioma cells." (PMID 38612895, 2024). "Inhibition of STAT3 activation has shown promise in reducing glioma cell proliferation, inducing apoptosis, and inhibiting tumor invasion in preclinical models, potentially overcoming therapeutic resistance and improving patient outcomes." (PMID 39063221, 2024). "qRT-PCR was employed in the present study to evaluate STAT3 expression levels in twenty sets of clinical glioma tissues and their corresponding normal brain tissues." (PMID 38238515, 2024). "The hypoxic glioma-derived EV-mediated delivery of Mir-1246 polarizes the macrophages toward M2 by inhibiting NF-κB and activating the STAT3 pathway." (PMID 39061140, 2024). "The present study outcomes revealed that miR-410 exerted a suppressive impact on glioma proliferation and apoptosis partially by targeting STAT3." (PMID 38238515, 2024). "Further experiments have substantiated the regulation of glioma pyroptosis by EZH2 through STAT3 inhibition (SH-4–54) and recovery (RO8191)." (PMID 39069522, 2024).